ZNF653 (zinc finger protein 653)
Description:
Transcriptional repressor. May repress NR5A1, PPARG, NR1H3, NR4A2, ESR1 and NR3C1 transcriptional activity.
Synonyms: ZIP67; E430039K05Rik
Tractability: Antibody: its Gene Ontology location is reachable by antibodies, with medium confidence.
Gene: Protein-coding gene on chromosome 19 (11,483,427 to 11,505,839, reverse strand). Ensembl gene ENSG00000161914.
Subcellular location: Nucleus
Subcellular location (Human Protein Atlas): Nucleoplasm
Gene Ontology:
Molecular function: AF-2 domain binding; DNA-binding transcription factor binding; protein binding; transcription corepressor activity; transcription coregulator activity
Biological process: extracellular negative regulation of signal transduction; negative regulation of transcription by RNA polymerase II; regulation of transcription by RNA polymerase II
Cellular component: nucleoplasm; nucleus; extracellular region
Genetic constraint (gnomAD): Loss-of-function variants: 37 observed, 51.34 expected, observed/expected ratio (o/e) 0.72, 90% interval 0.55 to 0.95. The synonymous counts are far from expectation, so gnomAD's model fits this gene poorly and the ratio says little. Missense variants: 808 observed, 833.83 expected, observed/expected ratio (o/e) 0.97, 90% interval 0.91 to 1.03. Synonymous variants: 435 observed, 352.69 expected, observed/expected ratio (o/e) 1.23, 90% interval 1.14 to 1.34.
Homologues: Orthologues: chimpanzee ZNF653 (99% identical), macaque ZNF653 (98% identical), dog ZNF653 (95% identical), pig ZNF653 (94% identical), mouse Zfp653 (93% identical), rat Zfp653 (91% identical), guinea pig ZNF653 (90% identical), tropical clawed frog znf653 (50% identical), zebrafish znf653 (40% identical). Paralogues in human: ZNF276 (20% identical), ZNF692 (20% identical), ZFP91 (19% identical), PRDM1 (14% identical), ZBTB16 (12% identical), ZNF76 (11% identical), PATZ1 (11% identical), ZBTB20 (11% identical), ZNF410 (11% identical), ZNF143 (11% identical), ZNF362 (11% identical), ZNF451 (11% identical), and 24 more.
Diseases named in the same sentence as ZNF653 in open-access papers:
ZNF653 is named in the same sentence as 2 diseases in open-access papers, as found by Europe PMC text mining. Sharing a sentence is not in itself a finding about the gene and the disease. The quoted sentences say what the papers report.
breast carcinoma (1 paper, 2021). "Multivariate Cox regression analysis of the two databases showed that high expression of ZNF644 and low expression of ZNF341, ZNF541, and ZNF653 were associated with radiosensitivity of breast cancer." (PMID 34504527, 2021). "High expression of ZNF644 and low expression levels of the other 3 genes (ZNF341, ZNF541, and ZNF653) were related to the radiosensitivity of breast cancer." (PMID 34504527, 2021). "High expression of ZNF644 might be associated with the radiosensitivity of breast cancer patients, and reciprocally, low expression of the other 3 genes (ZNF341, ZNF544, and ZNF653) marked patients in the radiosensitive group." (PMID 34504527, 2021).
ZNF653 also shares sentences with these, for which no sentence is quoted: cancer (1 paper).